GSDMD (gasdermin D)
Diseases named in the same sentence as GSDMD in open-access papers (continued):
Sharing a sentence is not in itself a finding about the gene and the disease.
infection (continued). "Likewise, GSDMD is necessary for the release of cleaved IL-1β during infection but is not required for IL-1β processing within cells." (PMID 35563469, 2022). "Microscopy observations showed that infection of neutrophils with the pyroptotic strain PP34ExoUS142A efficiently induced histone citrullination and DNA decondensation in WT neutrophils, but not in GsdmD-/- neutrophils." (PMID 35849616, 2022). "We noticed that in Nlrc4-/- and GsdmD-/- neutrophils, citrullination was not fully abrogated, suggesting that minor alternative pathways might also promote histone citrullination upon infection with P. aeruginosa pyroptotic strains." (PMID 35849616, 2022). "They proposed that GSDMD is activated either by neutrophil proteases that play a role in NETosis and can cleave GSDMD to its active fragments or by caspase-11-mediated GSDMD cleavage after cytosolic infection by gram-negative bacteria." (PMID 34122445, 2021). "GSDMD is also cleaved by caspase-11 in mice and by caspase-4 and caspase-5 in humans, which are activated by the so-called noncanonical inflammasome pathway in response to LPS stemming from infections with cytosolic Gram-negative bacteria." (PMID 32345661, 2020). "Pyroptosis is a lytic inflammatory cell death induced by inflammation or infection, which is mainly mediated by Caspase1 (the classical pathway: activated via PRRs sensing DAMPs or PAMPs) or Caspase4/5/11 (the non-classical pathway: directly activated by pathogens) by gasdermin D (GSDMD)." (PMID 40520010, 2025). "Furthermore, intracellular HAdV DNA level in siCASP4+5 vs siNC-transfected and siGSDMD vs siNC-transfected dTHP-1 cells are comparable at different timepoints post-infection, indicating that silencing of caspase-4/5 and GSDMD did not affect the HAdV replication." (PMID 37180156, 2023). "However, although caspase-8 was cleaved in TNF/SM treated macrophages and neutrophils, caspase-8 was not cleaved following PAO1 infection, indicating that there is no requirement for caspase-8 in GSDMD processing or IL-1β secretion induced by PAO1 infection of neutrophils." (PMID 37730693, 2023). "Moreover, C. violaceum ΔcopC infection triggered evident cleavage of GSDMD in HeLa cells, comparable to that in WT C. violaceum-infected cells, and additional expression of CopC in C. violaceum ΔcopC did not affect the level of GSDMD cleavage." (PMID 35446120, 2022). "The non-canonical inflammasome is essential for pyroptosis and IL-1β maturation in response to infection with certain gram-negative bacterial pathogens, or the delivery of cytoplasmic LPS, and occurs as a consequence of the caspase-11 dependent cleavage of gasdermin-D (GSDMD) and pannexin-1." (PMID 28570638, 2017). "Cytosolic lipopolysaccharide and intracellular gram-negative bacteria can activate the caspase-11/GSDMD pathway in neutrophils, leading to GSDMD-dependent NET release and protection against cytosolic infection." (PMID 41294351, 2026). "When GSDMD was suppressed, GSDME cleavage and activation remained largely constant following Brazil/78 and HKx31 infection compared to the non-targeting (NT) control." (PMID 40481027, 2025). "The results showed that caspase-3 in HMEC-1 cells was processed into its active form only during the late stages of infection, and no phosphorylated MLKL (a marker of necroptosis) or activated GSDMD (a marker of pyroptosis) was detected." (PMID 40607949, 2025). "In NLRC4 KO, NLRP3 KO, and WT THP-1 cells, GSDMD cleavage occurred even when the axoU gene was disrupted, while in the NLRC4/NLRP3 KO THP-1 no pyroptosis occurred upon infection with wildtype or AC055pGPI-axoU." (PMID 37598340, 2023). "Similar to what was observed in SH‐SY5Y cells, the NPCs did not express GSDMD but induced significant cleavage of CASP3, PARP, and GSDME following infection, and this led to necrotic cell death." (PMID 37646198, 2023).
infection (continued). "As the study has shown, GSDMD deficiency reduces the secretion of IL-1β and IL-18 in not all infections, so whether GSDMD can promote the protective inflammatory triggered by pro-inflammatory cytokines (such as IL-1β and IL-18) in vivo after SEZ infection remains to be further studied." (PMID 36311722, 2022). "Unlike the pattern observed in the liver, only splenic caspase-1, IL-1β, and GSDMD increased during S. mansoni infection; whereas levels of NLRP3 and IL-18 did not increase during infection." (PMID 34161342, 2021). "However, different from GSDMD, GSDME knockout did not have a significant impact on PDCoV multiplication at all tested time points (12, 18, and 24 h post-infection)." (PMID 40503916, 2025). "Interestingly, while suppression of gasdermin expression did not affect virus titers at 24 h post infection, viral titers were higher at 48 hpi in NHBE cells silenced for GSDMD or GSDME compared to cells treated with control siRNA." (PMID 37680489, 2023). "Notably, Δ6 Yptb infection led to robust GSDMD cleavage in WT Caco-2 cells, which was completely absent in CASP4−/− Caco-2 cells, indicating that caspase-4 is required for GSDMD cleavage in human IECs in response to Yersinia lacking its secreted effectors." (PMID 37615436, 2023). "Type I interferons (IFNs) are well-characterized anti-viral agents, and new data showed that GSDMD mediates the non-canonical release of IFN-β and an enhanced response to IFN-stimulated genes during transmissible gastroenteritis virus and porcine delta coronavirus (pDCoV) infection in vitro." (PMID 35844522, 2022).
cancer (168 papers, 2013 to 2026). A tumor composed of atypical neoplastic, often pleomorphic cells that invade other tissues. "These analyses provided a deeper understanding of the potential roles of HIC1 and GSDMD in different cancers and their underlying interactions." (PMID 40279559, 2025). "Pearson correlation analysis revealed that GSDMD expression was significantly associated with TMB in several cancer types." (PMID 40491921, 2025). "Lastly, we developed a NanoBiT biosensor for GSDMD, a critical effector in pyroptosis linked to cancer and inflammation-related diseases." (PMID 39727835, 2024). "While the release of IL-1β is directly linked to the progression of several types of cancers, the role of GSDMD in cancer is less clear." (PMID 39224600, 2024). "Blockade of Ca2+ influx by a Ca2+ chelator prevents ESCRT-mediated membrane repair and enhances GSDMD-caused pyroptosis in cancer cells." (PMID 38898209, 2024). "Accordingly, we found that cleaved gasdermin D-high/CHMP4B-low cancer was significantly associated with favorable RFS (log-rank p = 0.021) and tended to have a favorable OS (log-rank p = 0.128)." (PMID 38562170, 2024). "Some drugs can cause cleavage GSDMD or other gasdermin members cause pyroptosis and suppress cancer growth and development." (PMID 36867378, 2023). "In CRC, GSDMD has been found to be correlated with the abundance of pro-inflammatory bacteria, such as Bacteroides, which promote the risk of cancer development." (PMID 38002346, 2023). "Immune infiltration and single-cell analyses indicated that GSDMD was positively associated with an immunosuppressive microenvironment with more infiltrated macrophages and cancer-associated fibroblasts." (PMID 37371484, 2023). "We then performed the lactate dehydrogenase (LDH) cytotoxicity assay to evaluate the cancer-cell-specific cytotoxicity of our MITA-containing GSDMD-encoding circRNAs." (PMID 37938567, 2023). "A prognostic model based on four cancer stem cell-related gene signatures has been developed for pancreatic ductal adenocarcinoma, revealing that high expression of the GSDMD gene is associated with unfavorable outcomes (AUCs: 1 year: 0.722; 2 years: 0.862)." (PMID 38002346, 2023). "Knockdown of MLL4 causes a notable increase in GSDMD level in three out of four selected human cancer cell lines with distinct tissue origins." (PMID 36323669, 2022). "In particular, the genes B4GALT5 and GSDMD, which harbour three of the most significant variants, are closely related to cancer progression and the elevation of CA19-9 levels." (PMID 34071263, 2021). "Pan-cancer analysis showed that GSDMD-mediated pyroptosis might have a critical role in cancers such as adrenocortical carcinoma and CRC and is associated with the prognosis." (PMID 39062587, 2024). "Additionally, somatic mutations in GSDMD itself have been reported in certain cancers, suggesting a direct link between GSDMD mutations and disease progression." (PMID 38002346, 2023). "Further investigation showed that patients with different risk score may be sensitive to different anti-cancer drugs based on GSDMD." (PMID 36647032, 2023). "However, it is necessary to perform a functional analysis of the relationship between the GSDMD-enh3 and GSDMD in order to determine the underlying relationship between the GSDMD-enh3 and cancer." (PMID 35008400, 2022). "However, there are also various loss‐of‐function (LOF) mutations of GSDMD in different cancers, although this is less common than the epigenetic suppression of GSDME." (PMID 34459122, 2021). "IRF2 regulation of GSDMD levels may represent a critical regulatory axis in cancer cell death, given that its loss in cancer leads to immune evasion and resistance to immunotherapy." (PMID 33840390, 2021).
cancer (continued). "Furthermore, although TLR ligands play an important role for the priming of the inflammasome machinery and represent a promising strategy in cancer immunotherapy, we showed that GSDMD deficiency had only a minor effect on immune activation by TLR ligands in vitro and in vivo." (PMID 39224600, 2024). "By investigating the biological functions and regulatory mechanisms of GSDMD in various cancers, this study aims to enhance our understanding of its involvement in tumorigenesis, progression, and treatment response." (PMID 40491921, 2025). "Given its involvement in multiple stages of cancer development and progression, GSDMD represents a promising therapeutic target for cancer treatment." (PMID 40491921, 2025). "This review systematically examines the cellular and molecular complexities of GSDMD-mediated pyroptosis, with a particular emphasis on its roles in inflammation-related diseases and cancer." (PMID 39994107, 2025). "In this study, we conducted a comprehensive analysis of the role of the GSDMD gene in cancer prognosis, immunity, and drug therapy from both a pan-cancer and single-cell perspective." (PMID 40491921, 2025). "Pyroptosis, a form of programmed inflammatory cell death primarily mediated by gasdermin-D (GSDMD), has been implicated in ALI, cardiovascular diseases, and cancer." (PMID 39957615, 2025). "In contrast, under immune-activated conditions, NLRP3-mediated pyroptosis—particularly through gasdermin D (GSDMD)-dependent pore formation—can induce cancer cell death and enhance antitumor immune responses." (PMID 40718836, 2025). "GSDMD activation in intratumoral CD4+ T cells is associated with favorable prognosis and improved response to anti–PD-1 immunotherapy in human cancers." (PMID 40759573, 2025). "Despite these complexities, GSDMD holds significant promise as a therapeutic target for inflammation-related diseases and cancers, with the development of GSDMD inhibitors presenting a wide range of applications." (PMID 39994107, 2025). "As a key player in inflammation due to its role in activating the caspase system, GSDMD has been shown to be involved in cancer pathogenesis." (PMID 40418140, 2025). "This study examines the anti-cancer effects of usenamine A in LUAD and identifies the underlying mechanism involving the activation of NLRP3/caspase-1/GSDMD-mediated pyroptosis." (PMID 38265972, 2024). "CD147 is a hub Ag that binds to other proteins (Intergrin, Hyaluronan, CD44, P‐gp/ABCB1, ABCG2, MCT‐1/4, CypA/B, and Gasdermin D) to drive the malignancy of cancer cells." (PMID 38469549, 2024). "Polymyxin VI (PPVI) uses the ROS/NF‐κB/NLRP3/GSDMD signalling axis to awaken caspase‐1 to complete the cleavage mission of GSDMD to promote pyroptosis in NSCLC cancer cells, demonstrating the potential of PPVI for inhibiting NSCLC progression." (PMID 38652105, 2024). "For example, combined with ruthenium (II) polypyridyl complex Δ-Ru1, taxol improved caspase-1/GSDMD induced pyroptosis in Taxol-resistant cancer cells." (PMID 39300122, 2024). "CTSG exhibits functional diversity in cancer, activating pro-caspase-7, interactng with gasdermin D (GSDMD) to promote regulated cell death, and enhancing neutrophil migration by converting proMMP-1 to active MMP-1." (PMID 39736788, 2024). "Under near‐infrared light, the dual‐type photosensitised agent YBS produces multiple reactive oxygen species (ROS) on the cancer cell membrane, effectively triggering caspase‐1/GSDMD pathway‐induced immunogenic pyroptosis." (PMID 38594879, 2024). "They identified a specific small molecule agonist of GSDMD, quinoxaline 6,7-dichloro-2-methylsulfonyl-3-N-tert-butylaminoquinoxaline (DMB), which can directly activate GSDMD-mediated cancer cell pyroptosis." (PMID 39587093, 2024). "Although an effective technique to deliver GSDMD protein to cancer cells presents a challenge, EV-mediated delivery of functional GSDMD mRNA to cancer cells offers a promising solution." (PMID 38505610, 2024).
cancer (continued). "For instance, lower GSDMD expression in gastric cancer cells compared to adjacent non‐cancer cells suppresses pyroptosis in tumour cells, fostering cancer cell proliferation." (PMID 38594879, 2024). "Researchers also detected an increased level of gasdermin D N-terminal domain (GSDMD-N) and cleaved caspase-1 within the cancer cells, suggesting the existence of the caspase-1/GSDMD pathway of pyroptosis." (PMID 39398428, 2024). "Future extensive studies are required to elucidate the comprehensive role of GSDMD in different cancers at different stages for the development of potent anti-cancer therapies." (PMID 39253076, 2024). "In a study using near infrared (NIR) nanomicelles with combined PDT and PTT characteristics for cancer treatment, caspase-1/GSDMD-dependent pyroptosis was also identified in the treatment process." (PMID 39398428, 2024). "This biosensor allowed for the quantification of GSDMD’s intramolecular interaction and levels both in vitro and in vivo, exemplifying NanoBiT’s potential in cancer research and therapeutic validation." (PMID 39727835, 2024). "GSDMD activation was also observed in human cancers of the kidney, lung, bladder, uterus, and ovary." (PMID 38898209, 2024). "The expression of GSDMD mRNA in different types of cancer was first compared with its expression in the corresponding healthy tissues." (PMID 39224600, 2024). "The cancer cell pyroptosis also leads to the activation of capase‐1/GSDMD pathway in macrophages with proinflammatory cytokines release, triggering cytokine release syndrome." (PMID 37125240, 2023). "In most cases, various chemicals initiate GSDMD-mediated pyroptosis in different cancer cells; however, few of these research works focus on the downstream events of pyroptosis." (PMID 36932407, 2023). "We will explore the current understanding of GSDMD as a potential biomarker for different diseases, including infectious diseases, inflammatory disorders, and cancer." (PMID 38002346, 2023). "The other players in the inflammasome pathway such as Gasdermin-D are is also involved in the macrophage inflammasome-dependent proliferation of cancer where lung metastasis in Gasdermin D -/- mice was reduced." (PMID 37449203, 2023). "Suppression of GSDMD inhibited the activation of EGFR/Akt signal in cancer cells and impede their proliferation." (PMID 36161280, 2023). "At present, many studies have shown that GSDMD plays an important role in the occurrence and development of various cancers." (PMID 37483501, 2023). "The process by which pyroptosis and GSDMD affect cancer is still not fully understood, and further in vivo or clinical verification studies are urgently needed." (PMID 38002346, 2023). "Compared MscL with MLKL or GSDMD, it has more simple mechanism and specific activation, making it easy for non-invasive cancer treatment by ultrasound." (PMID 36936526, 2023). "Future studies should aim to explore the specific molecular mechanisms through which GSDMD contributes to different cancer outcomes." (PMID 38002346, 2023). "Despite the importance of pyroptosis has been recognized in cancers, the unique mechanism of GSDMD in tumor growth, invasiveness, and metastasis still needs future exploration." (PMID 35774778, 2022). "GSDMD is the most studied protein in pyroptosis, which is mainly expressed in immune cells, placenta, gastrointestinal epithelial cells, various cancers, and Jurkat T and Ramos B cancer cell lines." (PMID 35647057, 2022). "Our analysis of TGGA data demonstrated that GSDM genes (GSDMB, GSDMC, and GSDMD in particular) were upregulated in different types of cancers compared with the corresponding normal specimens." (PMID 36003332, 2022). "The pyroptosis regulators with CNV amplification were significantly more highly expressed in cancer cells (e.g., GSDMD), whereas the regulators with CNV deletion were significantly less expressed (e.g., CASP1, CASP3, and CASP4)." (PMID 35620284, 2022).